MIR941-3 (microRNA 941-3)
Synonyms: hsa-mir-941-3; MIRN941-3
Gene: MicroRNA gene on chromosome 20 (63,919,561 to 63,919,632, forward strand). Ensembl gene ENSG00000283513.
Homologues: Paralogues in human: MIR941-5 (100% identical), MIR941-2 (22% identical), MIR941-4 (0% identical).